TEX22 (testis expressed 22)
Tractability: No criterion of Open Targets' tractability assessment is met for any kind of drug.
Gene: Protein-coding gene on chromosome 14 (105,398,525 to 105,450,106, forward strand). Ensembl gene ENSG00000226174.
Subcellular location: Cytoplasm; Cytoplasmic vesicle, secretory vesicle, acrosome
Gene Ontology:
Cellular component: acrosomal vesicle; cytoplasm
Genetic constraint (gnomAD): Loss-of-function variants: 18 observed, 11.74 expected, observed/expected ratio (o/e) 1.53, 90% interval 1.04 to 1.93. The upper end of that interval is the gene's LOEUF score, 1.93, which puts it in group 6 of 6, group 1 being the genes least tolerant of losing a copy. Missense variants: 220 observed, 176.07 expected, observed/expected ratio (o/e) 1.25, 90% interval 1.12 to 1.4. Synonymous variants: 97 observed, 84.56 expected, observed/expected ratio (o/e) 1.15, 90% interval 0.97 to 1.36.
Homologues: Orthologues: chimpanzee TEX22 (97% identical), macaque TEX22 (91% identical), pig TEX22 (62% identical), dog TEX22 (53% identical), mouse Tex22 (52% identical), rat Tex22 (51% identical).